RNU6-192P (RNA, U6 small nuclear 192, pseudogene)
Gene: Small nuclear RNA gene on chromosome 20 (17,903,762 to 17,903,861, forward strand). Ensembl gene ENSG00000212555.
Homologues: Orthologues: macaque U6 (97% identical), pig U6 (81% identical), pig U6 (80% identical), pig U6 (74% identical), pig U6 (71% identical), mouse Gm22056 (66% identical). Paralogues in human: RNU6-463P (80% identical), RNU6-737P (80% identical), RNU6-774P (80% identical), RNU6-86P (80% identical), RNU6-1011P (79% identical), RNU6-1158P (79% identical), RNU6-169P (79% identical), RNU6-207P (79% identical), RNU6-28P (79% identical), RNU6-38P (79% identical), RNU6-552P (79% identical), RNU6-73P (79% identical), and 1286 more.